EPO (erythropoietin)
Diseases named in the same sentence as EPO in open-access papers (continued):
Sharing a sentence is not in itself a finding about the gene and the disease.
Hypertension (continued). "Moreover, we lack of statistical adjustment on the medication regimen of complications (such as diabetes and hypertension) and EPO, which may introduce residual confusion and affect the reliability of the results." (PMID 41517734, 2026). "Moreover, the effect on blood viscosity is also a mechanism of hypertension in EPO." (PMID 40000368, 2025). "There is a significant reduction in the supply of oxygen to the tissues in vasoconstriction-induced hypertension due to an increased level of erythropoietin (EPO), an oxygen-sensing protein, which may alter the process of angiogenesis if not kept within normal limits." (PMID 40951009, 2025). "Sympathetic overactivity, the renin-angiotensin-aldosterone system (RAAS), endothelium-derived mediators, erythropoietin-stimulating agents, dialysis-specific factors, and arterial stiffness have also been hypothesized to play a role in intradialytic hypertension." (PMID 38883013, 2024). "It should be taken into consideration that several common simultaneous disorders such as diabetes mellitus or hypertension, not only due to adverse reactions of related drugs but also because of the own pathophysiology impact, can impair the function of the kidney as a main production source of EPO." (PMID 37117600, 2023). "However, erythropoietin treatment is recognized to cause hypertension in CKD, thus, it is not an ideal drug for uremic cardiomyopathy." (PMID 35903671, 2022). "Hypertension that developed as a result of erythropoietin therapy can be controlled by conventional antihypertensive therapy, but if it persists, then reduction in the dose of erythropoietin or its temporary discontinuation may be needed." (PMID 33628672, 2021). "Furthermore, mice with ectopic transgenic EPO expression exhibited elevated eNOS activity and plasma NO level that prevented cardiovascular disease such as hypertension and thromboembolism and inhibition of NO synthase resulted in cardiovascular dysfunction and death." (PMID 24918289, 2014). "The other reason for the development of hypertension due to non-optimal EPO levels is the stated effect of its vasoconstrictor on tiny-resistance vessels, which provides an inverse effect over the acetylcholine-induced vasodilatory mechanism." (PMID 40951009, 2025). "Daprodustat and roxadustat showed reduced hypertension rates (daprodustat OR: 0.79; 95% CrI: 0.59 to 1.04), supporting the hypothesis that HIF-PHIs maintain more physiological erythropoietin levels, avoiding supraphysiologic peaks seen with ESAs." (PMID 41249974, 2025). "Thyroid status did not affect dialysis adequacy, but hypertension and the use of erythropoietin were more prevalent among hypothyroid patients." (PMID 36655149, 2023). "In both cases, grade 3 hypertension arose after doubling EPO administration because of absent response to 40,000 U/week." (PMID 35329991, 2022). "It is also uncertain if the increase in blood pressure is omnipresent at high altitude, if it is dependent on high erythropoietin levels or not and if hypertension affects the GFR." (PMID 37675017, 2022). "The Organization for improving the prognosis of Global Kidney Disease recommends that EPO treatment should not be stopped or interrupted because of high blood pressure (Drüeke and Parfrey, 2012)." (PMID 32848738, 2020). "Mice expressing high level of transgenic human EPO with elevated hematocrit and increased NO production also have elevated ET-1 levels, but do not exhibit hypertension." (PMID 32038269, 2019). "Both renal specific medications (e.g. phosphate binders, erythropoietin), and other generic/non-renal medications (e.g. medication for extra-renal morbidity such as hypertension) were studied." (PMID 24586478, 2014). "Seventeen patients with stage 4 CKD (estimated glomerular filtration rate 21.9±7.4 mL/min per 1.73 m2) with controlled hypertension who were aged 63.5±13 years and had not been treated with EPO were included in the study." (PMID 23584809, 2013).
Hypertension (continued). "It is advisable that patients with uncontrolled hypertension do not participate in trials of EPO in AKI." (PMID 21906325, 2011). "Thus, the results showed that hypertension induced by erythropoietin was independent of hyperviscosity." (PMID 33628672, 2021). "There is no clear consensus on the role of blood viscosity in erythropoietin-induced hypertension." (PMID 33628672, 2021). "In animal models, mice expressing high level of transgenic EPO (tg6) with high hematocrit did not develop hypertension due to markedly increased levels of eNOS and NO in vascular tissue and in the circulation, and EPO treatment in rodents was also observed to stimulate NO production." (PMID 24918289, 2014). "However, EPO is not without detrimental effects such as during hypertension, vascular disease, and cancer progression." (PMID 23029019, 2012). "In addition, sustained bone marrow stress in long-standing hypertension may drive the premature release of juvenile erythrocytes, while impaired erythropoietin signaling under inflammatory conditions further disrupts normal red cell maturation." (PMID 41231809, 2025). "The underlying molecular mechanisms are incompletely understood, but may involve atherosclerosis, vascular dysfunction, hypertension, type 2 diabetes, history of cardiac disease, and total homocysteine, and possibly, lack of erythropoietin formation by the kidney." (PMID 29417476, 2018).
diabetes (145 papers, 2008 to 2026). "The findings align with existing literature, highlighting the role of genetic variations in the EPO locus in influencing DR susceptibility, a major complication of diabetes." (PMID 41196916, 2025). "Renal dialysis, erythropoietin therapy, diabetes, and hypothyroidism have been found to be associated with an increased risk for promoting MRONJ." (PMID 37048016, 2023). "To the best of our knowledge, we are the first to examine associations between fetal hypoxia, as evidenced by AF EPO concentrations, and long-term offspring health outcomes in pregnancies affected by diabetes." (PMID 34777246, 2021). "After loosening erythropoietin payment criteria, the erythropoietin dosage increased and the cardiovascular risk decreased; however, the reduction in cardiovascular risk was observed only in patients with diabetes." (PMID 33331829, 2020). "As such, haplotype analysis was performed to further explore the relationship between EPO variations and diabetes mortality risk." (PMID 31316151, 2019). "The aim was to determine if EPO protects against hippocampal neurodegeneration as well as impairment of cognition and motor performance, associated with long-term diabetes." (PMID 30597853, 2018). "The effects of EPO (300 U/kg administered three times a week for 4 weeks) on diabetes-associated cognitive decline were investigated in diabetic rats." (PMID 28584284, 2017). "While there is now ample evidence indicating that EPO is beneficial against various types of brain injury, little is known about the effects of EPO in diabetes-associated cognitive dysfunction." (PMID 28584284, 2017). "For stillbirth, research to identify better predictors of placental dysfunction such as erythropoietin, pregnancy associated plasma protein A, alpha fetoprotein and angiogenic/antiangiogenic factors in women with diabetes is needed." (PMID 28597075, 2017). "Several studies indicate that erythropoietin (EPO) has remarkable neuroprotective effects in various central nervous system disorders, while little is known about the effects of EPO in diabetes-associated cognitive dysfunction." (PMID 28584284, 2017). "The effect of EPO on diabetes-associated spatial learning and memory impairment was evaluated using the Morris water maze test." (PMID 28584284, 2017). "In this study, we evaluated the effect of EPO on diabetes-associated cognitive dysfunction using in vitro and in vivo models, and we then examined the mechanisms underlying the neuroprotective effects of EPO." (PMID 28584284, 2017). "This is attributed to iron and EPO deficiencies, hyporesponsiveness to EPO, and hypoxia associated with diabetes." (PMID 27310973, 2016). "The genetic variant rs1617640 in the EPO gene was investigated in three American studies in which one study included type 2 diabetes mellitus whereas other two were for type 1 diabetes mellitus." (PMID 25280384, 2014). "Resistance to ESAs (erythropoietin stimulating agents) is highly prevalent in hemodialysis patients with diabetes and associated with an increased mortality." (PMID 23521816, 2013). "However, in a previous study, it has been reported that EPO decreases blood glucose levels in obese mice that are susceptible to diabetes and obesity through decreasing body weight and lowering hemoglobin A1c." (PMID 39338226, 2024). "However, because of iron and erythropoietin deficiencies, hyporesponsivenss to erythropoietin, and the hypoxia associated with diabetes, the long-term effect of Roxadustat on renal outcomes in patients with diabetes and CKD requires further study." (PMID 35188068, 2022). "EPO was also associated with improved diabetes-associated cognitive dysfunction in male rodents." (PMID 34603036, 2021). "Systemic inflammation, reduced red cell survival, functional erythropoietin deficiency, and erythropoietin resistance caused by renal tubular dysfunction in patients with diabetes may lead to insufficient erythropoietin response." (PMID 32454794, 2020).
diabetes (continued). "Although the pathophysiology of type 1 and type 2 diabetes per se is very different, we did not detect any major variation of the associations of hepcidin and EPO and also of both with the investigated outcomes when the type of diabetes was investigated in detail." (PMID 25894587, 2015). "We found hepcidin-25 to be associated with EPO and impaired kidney function in diabetic CKD." (PMID 25894587, 2015). "The study suggested that before development of nephropathy, overt inflammation associated with diabetes may culminate erythropoietin suboptimal response." (PMID 25695026, 2014). "In addition, other factors, such as diabetes mellitus, proteinuria, and low eGFRs, are associated with lower erythropoietin or Hb levels and may increase the susceptibility of patients to ESA resistance." (PMID 41270026, 2025). "Therefore, the present study aimed to investigate whether EPO has protective effects in the context of diabetes-associated cognitive dysfunction in vivo and in vitro, and to identify the possible mechanism underlying these effects." (PMID 28584284, 2017). "Therefore, the present study aimed to investigate whether EPO ameliorates diabetes-associated cognitive dysfunction in vivo and in vitro." (PMID 28584284, 2017). "However, the effects of EPO on diabetes-associated cognitive impairments and the mechanisms of such effects remained unknown." (PMID 28584284, 2017). "The effect of EPO on the circulatory system is often presented in the context of diabetes mellitus pathology, using various in vivo experimental models." (PMID 41157076, 2025). "Our previous study showed that long-term treatment with EPO exerted renoprotective effects in streptozotocin-induced type 1 diabetes mellitus." (PMID 40943240, 2025). "In rodent models of diabetes, EPO treatment contributed to improved cognitive dysfunction associated with hippocampal neurodegeneration." (PMID 39996752, 2025). "Chronic fetal hypoxia resulting from maternal and fetal hyperglycemia, indicated by the shown correlation between the concentration of erythropoietin in amniotic fluid and antenatal glycemic control, has been accounted for intrauterine death in diabetes." (PMID 38958733, 2024). "The reduced erythropoietin (EPO)-producing ability in patients with diabetes has been reversed after treatment with SGLT2 inhibitors." (PMID 37109553, 2023). "Of note, the concentration of EPO is relatively low in the serum of patients with diabetes or kidney diseases." (PMID 35656290, 2022). "Nevertheless, further studies will need to shed more light on how EPO affects the activity of osteoblasts and osteoclasts, and more specifically during diabetes." (PMID 33671138, 2021). "The chronic inflammatory status inherent to diabetes mellitus is being widely agreed in the scientific community as responsible for alterations in the synthesis and the presence of resistance to EPO." (PMID 33920401, 2021). "In mouse models of diabetes and obesity, EPO treatment in male mice with protein Tyr phosphatase knock out (PTP1B−/−) and in ob/ob mice decreased blood glucose and body weight gain." (PMID 34603036, 2021). "This experimental finding is consistent with the findings of increased systemic EPO levels and hemoglobin concentration (Hb)/hematocrit, in type 2 diabetes mellitus patients treated with this class of medication." (PMID 34184431, 2021). "This can be explained by the need for special storage of some medicines (eg, recombinant human erythropoietin for kidney disease or insulin for diabetes)." (PMID 32716892, 2020). "After loosening erythropoietin payment criteria, reduced cardiovascular risks were observed, particularly for patients with diabetes." (PMID 33331829, 2020). "Further research is needed to investigate why peritoneal dialysis patients with diabetes mellitus are more sensitive to the increase in erythropoietin dosage and Hct levels." (PMID 33331829, 2020).
diabetes (continued). "The highest average concentration of EPO in serum (9.95 mIU/ml) was determined in the group of people with diabetes with PDR." (PMID 31727007, 2019). "The average concentration of EPO in serum in the group of patients with diabetes with NPDR was 7.00 mIU/ml." (PMID 31727007, 2019). "The average concentration of EPO in serum in the group of people with diabetes with NPDR was 7.00 mIU/ml." (PMID 31727007, 2019). "The main aim of this work was to examine the possible influence of serum concentrations of erythropoietin on the development of diabetic retinopathy in patients with diabetes mellitus type 2." (PMID 31727007, 2019). "This study shows that 10 weeks of diabetes induced dilatation of blood capillaries, and this effect was augmented by EPO." (PMID 30597853, 2018). "In this study, it has been shown that chronic EPO treatment is protective against cognitive deficits and hippocampal neurodegeneration, associated with STZ-induced diabetes in BALB/c mice." (PMID 30597853, 2018). "The need for recombinant erythropoietin support or treatment of established diabetes also remained unchanged during therapy." (PMID 30246027, 2018). "Since tissue hypoxia is the major stimulus of EPO, this also implies a relationship between diabetes and fetal distress." (PMID 29898693, 2018). "For both diabetic groups blood glucose remained significantly higher compared to controls at the end of the study (unpaired t-tests: control versus diabetes: t = −30.24, p = 1.07 × 10−12; control versus EPO-treated diabetics: t = −17.23, p = 7.875 × 10−10)." (PMID 30597853, 2018). "Chronic EPO-treatment is protective against cognitive deficits and hippocampal neurodegeneration associated with 10-weeks of STZ-induced diabetes in BALB/c mice." (PMID 30597853, 2018). "Together, these findings suggest that EPO treatment improves spatial memory in long-term streptozotocin-induced diabetes." (PMID 30597853, 2018). "In the same context, diabetic rats had decreased renal mRNA expression of EPO as a result of oxidative stress due to diabetes." (PMID 30510626, 2018). "In EPO-treated diabetics, there was improvement in the cytoplasm of the cells as the cells appeared darker than the diabetes group with more ribosomes similar to that revealed in the control group." (PMID 30597853, 2018). "The aim of this study was to investigate the potential preventative effects of chronic EPO treatment on spatial learning and memory as well as histology of the hippocampus in a mouse model of diabetes." (PMID 30597853, 2018). "Our study has provided a strong basis for further investigation of the anti-obesity and diabetic effects of EPO, and we hope that this will contribute to the development of new safe and effective drugs against obesity and diabetes." (PMID 28288167, 2017). "In conditions associated with increased RBC breakdown, such as in the advanced trimesters of pregnancy, recent hemorrhage, intravascular hemolysis or transfusion or erythropoietin treatment, only blood glucose estimation should be used to diagnose diabetes." (PMID 28167928, 2017). "Previous studies that investigated the mechanism of EPO’s anti-obesity and anti-diabetes effect have focused mainly on white adipose tissue, muscle and liver." (PMID 28288167, 2017). "We know in animal studies that erythropoietin-stimulating agents (ESAs) protect against the development of diabetes through direct effects on pancreatic ß cells and have been associated with improvement in glucose tolerance." (PMID 27119016, 2016). "Studies have shown that erythropoietin-stimulating agents (ESAs) protect mice against the development of diabetes through direct effects on pancreatic ß cells." (PMID 27119016, 2016). "We analyzed interactions between hemoglobin and diabetes, UAE, eGFR and hs-CRP for the association with EPO." (PMID 25915923, 2015).